ESRP1 (epithelial splicing regulatory protein 1)
Diseases named in the same sentence as ESRP1 in open-access papers (continued):
Sharing a sentence is not in itself a finding about the gene and the disease.
tumor (79 papers, 2013 to 2026). "Consistent with this function, loss of ESRP1 is associated with EMT and increased tumor cell motility, while high levels of ESRP1 can drive a partial mesenchymal-to-epithelial reverting transition (MET)." (PMID 41155518, 2025). "Together, these data reveal the expression of two ACLY splice isoforms in mouse and human tissues and indicate that ACLY is a component of the splicing program mediated by ESRP1, a factor that has been implicated in tumor progression." (PMID 38815867, 2024). "This reciprocal interaction between ESRP1 and circPTPN12 forms a tumor-associated regulatory pathway." (PMID 38992675, 2024). "They further demonstrated that ESRP1 overexpression promotes tumor growth and metastasis in vivo, which is associated with the immunosuppressive effect of ESRP1 in the tumor immune microenvironment." (PMID 38110955, 2023). "ESRP1 expression was also associated with tumor-associated immune cytolytic activity and immunosuppression in the tumor immune microenvironment." (PMID 38110955, 2023). "The genes with increased expression levels in ESRP1 high tumours include MKI67 (encoding the proliferation marker Mki67); the cell cycle regulator encoding genes CDK1, CCNA2, and CCNB2; and BIRC5 that inhibits apoptosis." (PMID 37752235, 2023). "Alternative mRNA splicing of CD44 is mediated by epithelial splicing regulatory protein 1 (ESRP1), and several reports have suggested that the upregulation of ESRP1 is associated with poor prognosis of tumours." (PMID 33210459, 2021). "Among these circRNAs, because cESRP1 originates from the ESRP1 gene, which is closely linked to tumour-associated EMT, we selected cESRP1 to further investigate the role of cESRP1 in SCLC chemoresistance." (PMID 31728016, 2020). "Establishing the network between OS-related AS events and tumor-specific SFs, this research found that ESRP1 was associated with several OS-AS events that were correlated with OS." (PMID 32617077, 2020). "Herein, we explore the (epi)genetic regulation and expression pattern of FGFR2, its isoforms and splicing regulator ESRP1, in normal and tumor stomach samples, and potential associations with clinico-pathological and survival data." (PMID 31881796, 2019). "Results indicate that ESRP1 regulate in CRC multiple mesenchymal specific gene transcript splice variants important for tumor progression." (PMID 27650542, 2016). "Reduction of ESRP1 in tumor cells was evaluated by immunohistochemistry, associated with microsatellite stability and switch to mesenchymal splice signatures of FGFRs, CD44, ENAH and CTNND1(p120-catenin)." (PMID 27650542, 2016). "In contrast, our data showed that high ESRP1 as well as ESRP2 in tumor tissue are associated with favorable overall survival outcome." (PMID 27650542, 2016). "Integrin α6β1 drives TNBC tumor initiation by mediating the activation of autocrine signals, while the autocrine VEGF signaling pathway maintains the expression of the α6B variant by inhibiting the splicing factor ESRP1, thereby maintaining tumor stem cells and promoting tumor formation." (PMID 39239559, 2024). "Another study reported the effect of ESRP1 on tumor-associated macrophages in the TME." (PMID 38110955, 2023). "Therefore, it becomes compelling to unveil the regulatory mechanisms that underlie the increased ESRP1 level in the tumor tissues." (PMID 34362878, 2021). "Furthermore, our results suggested that ESRP1 played an important role in regulating tumor-associated macrophage polarization, dendritic cell infiltration, Treg cells, and T cell exhaustion." (PMID 32964032, 2020). "To understand whether FGFR2 and ESRP1 overexpression was associated with increased CN, we analyzed TvsN and unpaired tumor samples from cohort #1 dataset #8 and #9." (PMID 31881796, 2019). "Loss of ESRP1 in ~90% of AIPpos cases indicates that ESRP1 may be an important regulator of tumor invasiveness." (PMID 30867568, 2019).
tumor (continued). "We demonstrated with the studied patient cohort and the conditional cell model that expression of ESRP1 in CRC tumor cells is associated with a shift in EMT splicing patterns of ENAH and CTNND1 (p120-catenin), thus confirming a key role of ESRPs in CRC progression." (PMID 27650542, 2016). "Furthermore, we have shown that high ESRP1 expression may be associated with immune-suppression in tumor immune microenvironment in vivo." (PMID 32467669, 2020). "In addition to EMT, it has been reported that ESRP1 can inhibit tumor cell proliferation, but the exact cellular and molecular mechanisms underlying ESRP1-mediated inhibition of cell proliferation remain unknown." (PMID 31362365, 2019). "The expression levels of genes ESRP1, GRHL2, MTHFD2, RACGAP1, and SQLE, considered risk factors, were significantly up‐regulated in tumor tissues compared with normal tissues and were statistically significantly associated with a poor prognosis." (PMID 40586163, 2025). "Consistent with the potential tumor suppressor role of ESRP1 observed in this study, we found that ESRP1 expression is suppressed by promoter hypermethylation in RCC." (PMID 40866976, 2025). "To further validate the role of ESRP1 in vivo, we established the subcutaneous xenograft tumor model and three metastasis models in nude mice." (PMID 40528239, 2025). "ESRP1 can indirectly affect the activity of these pathways by regulating the expression of CD44 splice variants, thereby influencing tumor growth, invasion, and drug resistance." (PMID 40046628, 2025). "ESRP1 overexpression is negatively correlated with metastasis, tumor size, and clinical Stage in ADC patients." (PMID 40046628, 2025). "In conclusion, our findings revealed that ESRP1 is a novel tumor suppressor related to ferroptosis in DGC." (PMID 40528239, 2025). "By the cell‐specific splicing network and 1037 AS events, MRAS consistently highlighted ESRP1 as the top splicing regulator with upregulated expression in tumor cells." (PMID 40323145, 2025). "Conversely, ESRP1 high subgroup demonstrated preferential accumulation of tumor-reactive lymphocytes such as effector memory T cells (Tem), central memory T cells (Tcm), and natural killer (NK) cells." (PMID 40528239, 2025). "Low expression of ESRP1 leads to an increase in CD44s levels and a decrease in CD44v (variant CD44) levels, both of which play crucial roles in tumor development." (PMID 40046628, 2025). "Once tumors reached a palpable size, adeno-associated virus (AAV)/ESRP1 or AAV/Null was injected intratumorally, and AAV/ESRP1 significantly inhibited RCC tumor growth in mouse models." (PMID 40866976, 2025). "In this study, we identified a novel role for ESRP1 in DGC cells that impacts tumor progression through the regulation of ferroptosis processes." (PMID 40528239, 2025). "Consistent with the in vitro result, the tumor burden in ESRP1-overexpression group was reduced compared to the control group, suggesting that upregulated ESRP1 expression effectively inhabited tumor growth in nude mice." (PMID 40528239, 2025). "ESRP1 has been confirmed as a core regulator of EMT-related splicing events in human tumor metastasis." (PMID 40046628, 2025). "Consistent with the involvement of ESRP1 in the EMT, previous studies have reported the prognostic significance and role of ESRP1 in tumor progression." (PMID 38110955, 2023). "This study found that the ESRP1-overexpressing group has significantly heavier tumor weight and lower infiltrated CD8+ T cells than the empty vector group." (PMID 38110955, 2023). "In vitro, altered levels of ESRP1 or ESRP2 caused a switch of FGFR2 splicing between FGFR2-IIIb and FGFR2-IIIc, resulting in changes in tumor cell growth and metastatic potential." (PMID 37090731, 2023). "On the other side, ESRP1 can act as an oncogene, regulating the biological functions of tumor cells and leading to lower overall survival of breast cancer patients and increased lung metastasis of 4T1 cells." (PMID 38114495, 2023).
tumor (continued). "Patients with distant metastasis (M1, n = 7) show significant lower expression of ESRP1 than patients without distant metastasis (M0, n = 27), indicating that ESRP1 is negatively correlated with tumor metastasis." (PMID 38114495, 2023). "In vivo, increased ESRP1 or ESRP2 levels in BC cells not only inhibited the growth of the xenografted tumor formation in nude mice, but also reduced the occurrence of lung metastasis, partially through altering polarization of tumor-associated macrophages." (PMID 37090731, 2023). "This suggests that ESRP1 affects tumor progression through the dysregulation of cellular metabolism." (PMID 38110955, 2023). "In vivo, re-expression of ESRP1 or ESRP2 in BC cells not only inhibited the growth of the xenografted tumor formation in nude mice, but also reduced the occurrence of lung metastasis, partially through altering polarization of tumor-associated macrophages." (PMID 37090731, 2023). "We also performed immunohistochemical staining of Ecadherin in mouse lungs, and, as before, overexpression of ESRP1 promoted Ecadherin expression on tumor cells; however, knocking down CLSTN1-S impaired this effect." (PMID 38114495, 2023). "The results showed that the number of metastatic tumor nodules on the lungs of ESRP1-overexpressing group was significantly lower than that in the control group." (PMID 38114495, 2023). "The functions of ESRP1 and CLSTN1 as biomarkers have also been verified in clinical samples, providing the potential for screening individuals at risk of tumor metastasis and early clinical intervention." (PMID 38114495, 2023). "In vitro, altered ESRP1 or ESRP2 levels caused a switch of alternative splicing of FGFR2 between FGFR2-IIIb and FGFR2-IIIc, resulting in changes in tumor cell growth and metastatic potential." (PMID 37090731, 2023). "The analysis of AS changes indicates that ESRP1 and ESRP2 control the expression of exons that are associated with specific tumor molecular features and patient clinical outcomes." (PMID 35887187, 2022). "This is further supported by the correlation analysis performed in primary tumor data and by the strong ESRP1 and ESRP2 downregulation upon ERα silencing in hormone-deprived MCF-7." (PMID 35887187, 2022). "We show that, in CRC cells, ESRP1 binds to and has the same trend in expression as RAC1b, a well-known tumor promoter." (PMID 34439247, 2021). "It is thus crucial to fully dissect the molecular events regulated by ESRP1 in CRC in order to appropriately target tumor progression." (PMID 34439247, 2021). "We also demonstrate that ESRP1 is paradoxically downregulated in the hypoxic tumor milieu despite the abundance of E2F1." (PMID 34362878, 2021). "Consistent with our in vitro findings, overexpression of ESRP1 significantly reduced tumor volume and weight compared with those of the paired control group, whereas knockdown of ESRP1 led to the opposite results." (PMID 33495408, 2021). "The RNA binding protein Epithelial Splicing Regulatory Protein 1 (ESRP1) can act as a tumor suppressor or promoter in a cell type- and disease context-dependent manner." (PMID 34439247, 2021). "Silencing of RAC1b expression significantly reduced the number of soft agar colonies formed by ESRP1-overexpressing cells, suggesting that ESRP1 acted, at least partially, through RAC1b in its tumor-promoting activities in CRC cells." (PMID 34439247, 2021). "Analysis of the tumor and normal tissues from the TCGA PRAD samples showed that ESRP1 expression was significantly higher (p < 0.001) in the tumor samples than in the normal samples." (PMID 33194621, 2020). "The correlation between ESRP1 levels, clinical parameters, and tumor immune infiltration was comprehensively analyzed." (PMID 32964032, 2020). "Therefore, it was suggested that high ESRP1 may be associated with tumor immune suppression." (PMID 32467669, 2020).
tumor (continued). "The integrative proteomics-bioinformatics approach we employed unveils several potential oncogenic pathways activated by ESRP1 in this tumor." (PMID 31963158, 2020). "Tumor invasion, migration, colony formation and animal experiments were used to study the malignant biological behavior of ESRP1." (PMID 32467669, 2020). "ESRP1 acts as a regulator of alternative splicing events that help to suppress the EMT process in tumour progression." (PMID 32641707, 2020). "In lung ADC tissues, ESRP1 overexpression was inversely related to the presence of metastases, tumour size, and clinical stage of lung ADC." (PMID 32641707, 2020). "As ESRP1 shows a plastic behaviour during tumor development, proteins or genes regulated by ESRP1 are expected to undergo cell- and context-dependent modulation." (PMID 31963158, 2020). "In case of tumor heterogeneity, it cannot be excluded that more tumors are positive for ESRP1/2 than reported in our study." (PMID 33339518, 2020). "To gain more information about the potential functions of ESRP1 and its regulatory network, we performed target gene analyses of tumor data from public databases." (PMID 32964032, 2020). "This was also true for ESRP1, which displayed low levels of promoter methylation in almost all tumor samples and higher RNA expression than those with other methylation levels." (PMID 31881796, 2019). "FGFR2 and ESRP1 were co-amplified in up to 24% of TCGA tumors when tumor and normal samples were compared." (PMID 31881796, 2019). "To confirm this result, we further analyzed the expression of thymidine kinase 1 (TK-1) or CD44 isoforms in our system, as TK-1 is known to be a tumor proliferation marker, and ESRP1 is known to regulate CD44 isoform switching during the EMT." (PMID 31362365, 2019). "This study provides novel evidence that ESRP1 can induce tumor cell G1-phase cell cycle arrest by regulating cyclin A2 mRNA stability." (PMID 31362365, 2019). "Promoter methylation analysis of the region 2000bp upstream of the TSS of FGFR2 and ESRP1 revealed that most tumor samples from cohort #1 (datasets #3 and #4), cohorts #2, #3 and #4 were hypo/demethylated for both gene promoters." (PMID 31881796, 2019). "Our results not only highlight the molecular mechanisms of ESRP1 in the context of tumor cell proliferation, but further provide new insights with respect cyclin A2 post-transcriptional regulation." (PMID 31362365, 2019). "Although consequences of ESRP1-induced alternative splicing have been explored across several cancer types, showing both an oncogenic and tumor-suppressing effect, it has yet to be verified in GC." (PMID 31881796, 2019). "We observed that there was a significant correlation between tumor histotype and ESRP1 CN (p-value = 2.55 × 10−3): while most amplified tumors were of the intestinal type, almost 40% of samples with normal ESRP1 CN were diffuse-type GCs." (PMID 31881796, 2019). "Chromatin immunoprecipitation (ChIP) sequencing analysis at the ESRP1 locus has clarified that CD44v-positive tumor cells manifest the enrichment of H3K4me3 at the transcription start site, while CD44v-negative cells exhibit that of H3K27me3." (PMID 30053872, 2018). "Knockdown of FGFR2 expression in ESRP1-overexpressing Caco-2 cells reduced the size of the soft agar colonies showing that FGFR2 participated in anchorage-independent tumor growth." (PMID 28052020, 2017). "ESRP1 is a documented tumor suppressor but our analysis on CRC cell lines and TCGA expression datasets also revealed cases in which this RBP was overexpressed." (PMID 28052020, 2017). "(C) Kaplan-Meier survival curves of CRC patients with high (n = 77) or low (n = 88) expression of ESRP1 in tumor tissues." (PMID 28975893, 2017). "In conclusion, our data show, for the first time, that aberrantly high ESRP1 expression can drive tumor progression in CRC." (PMID 28052020, 2017).
tumor (continued). "This study investigates ESRP1 and 2 expression as well as alternative splicing patterns in paired tumor and non-tumor tissue of CRC patients and their correlation with clinical data." (PMID 27650542, 2016). "The positive association of ESRP expression with favorable prognosis in the studied CRC patient cohort is supported by the identification of ESRP1 as tumor suppressor." (PMID 27650542, 2016). "ESRP1 analyzed by IHC confirmed uniform protein expression in tumor cells as e.g. shown for CRC case #59." (PMID 27650542, 2016). "Our study supports the role of ESRP1 as tumor suppressor and strongly suggests that ESRPs are candidate markers for early detection, diagnosis, and prognosis of CRC." (PMID 27650542, 2016). "Hypermethylation of the DNA promoter region for RAB25 has been reported previously, and both RAB25 and ESRP1 have tumor-suppressive effects." (PMID 26646320, 2016). "Further mesenchymal and epithelial splicing events were analyzed from genes known as regulated by ESRP1 and important for tumor progression." (PMID 27650542, 2016). "Expression of ESRPs was significantly associated with favorable overall survival (log-rank test, P=0.0186 and 0.0408), better than prognostic stratification by tumor staging; and for ESRP1 confirmed with second TCGA cohort (log-rank test, P=0.0435)." (PMID 27650542, 2016). "ESRP1 (epithelial splicing regulatory protein 1), which regulates alternative splicing events in epithelial cells, also has tumor suppressor effects and is down-regulated during EMT." (PMID 26646320, 2016). "Tumor (T) and adjacent non-tumor (N) tissue from the resection border from patients diagnosed with CRC was studied by qPCR for relative expression of ESRP1 and ESRP2." (PMID 27650542, 2016). "Similarly, the ESRP1-overexpressing group exhibited a significantly lower number of metastatic tumor nodules in the lungs compared to the control group." (PMID 40528239, 2025). "Additionally, wound healing and Transwell assay indicated that silence of ESRP1 promoted the invasive and migrative ability in MKN45 cells, while overexpressing ESRP1 suppressed tumor invasion and migration in MKN45 cells and SUN484 cells." (PMID 40528239, 2025). "In addition, by regulating the expression of the CD44 variant, ESRP1 can also influence critical signaling pathways such as PI3K/AKT and Wnt/β-catenin, thereby participating in the regulation of the tumor microenvironment." (PMID 40046628, 2025). "Further research on the mechanism of action of ESRP1 in OSCC may help reveal the pathogenesis of this tumor and provide new targets and strategies for the treatment of OSCC." (PMID 40046628, 2025). "Additionally, through literature review, we have learned that ESRP1, as an epithelial-specific RNA-binding protein, can regulate tumor invasion and metastasis by influencing the EMT process." (PMID 40528239, 2025). "Our findings confirmed the tumor-suppressive role of ESRP1 in RCC." (PMID 40866976, 2025). "Therefore, ESRP1 has a significant impact on tumor occurrence, development, invasion, and metastasis by regulating the alternative splicing of CD44." (PMID 40046628, 2025). "ESRP1, a key component in tumor EMT, is generally downregulated in GC metastasis events." (PMID 38302461, 2024). "Furthermore, recent studies have reported that ESRP1 affects tumor growth by regulating the metabolism of tumor cells or immune cell infiltration in the tumor microenvironment, suggesting the novel roles of ESRP1 in addition to EMT." (PMID 38110955, 2023). "Importantly, ESRP1 was involved in the regulation of immune cells in the tumor microenvironment (TME)." (PMID 38110955, 2023). "In lung adenocarcinoma, ESRP1 inhibits tumor invasion and metastasis by regulating EMT." (PMID 38114495, 2023).